PMPCA (peptidase, mitochondrial processing subunit alpha)
Description:
Substrate recognition and binding subunit of the essential mitochondrial processing protease (MPP), which cleaves the mitochondrial sequence off newly imported precursors proteins.
Synonyms: INPP5E; KIAA0123; Alpha-MPP; MAS2; CLA1; CPD3; P-55; SCAR2
Tractability: PROTAC: ubiquitination databases record sites on it; its protein half-life has been measured.
Gene: Protein-coding gene on chromosome 9 (136,410,630 to 136,427,992, forward strand). Ensembl gene ENSG00000165688.
Subcellular location: Mitochondrion matrix; Mitochondrion inner membrane
Subcellular location (Human Protein Atlas): Mitochondria
Pathways (Reactome):
Metabolism of proteins: Mitochondrial protein degradation
Protein localization: Mitochondrial protein import
Transport of small molecules: Processing of SMDT1
Gene Ontology:
Molecular function: protein binding; metal ion binding; metalloendopeptidase activity
Biological process: protein processing; protein localization to mitochondrion; proteolysis
Cellular component: extracellular region; mitochondrial inner membrane; mitochondrion; mitochondrial matrix; mitochondrial processing peptidase complex
Genetic constraint (gnomAD): Loss-of-function variants: 31 observed, 37.65 expected, observed/expected ratio (o/e) 0.82, 90% interval 0.62 to 1.11. The upper end of that interval is the gene's LOEUF score, 1.11, which puts it in group 4 of 6, group 1 being the genes least tolerant of losing a copy. Missense variants: 596 observed, 578.27 expected, observed/expected ratio (o/e) 1.03, 90% interval 0.96 to 1.1. Synonymous variants: 276 observed, 236.49 expected, observed/expected ratio (o/e) 1.17, 90% interval 1.06 to 1.29.
Gene-disease validity (ClinGen):
ClinGen rates the evidence that PMPCA causes each of these diseases.
mitochondrial disease (autosomal recessive): Definitive.
Homologues: Orthologues: macaque PMPCA (98% identical), mouse Pmpca (91% identical), rat Pmpca (91% identical), dog PMPCA (90% identical), guinea pig PMPCA (89% identical), chimpanzee PMPCA (86% identical), pig PMPCA (84% identical), tropical clawed frog pmpca (82% identical), zebrafish pmpca (78% identical), Drosophila melanogaster CG8728 (50% identical), Caenorhabditis elegans mppa-1 (38% identical). Paralogues in human: PMPCB (29% identical), UQCRC1 (27% identical), UQCRC2 (23% identical), IDE (19% identical), NRDC (18% identical), PITRM1 (18% identical).
Diseases named in the same sentence as PMPCA in open-access papers:
PMPCA is named in the same sentence as 35 diseases in open-access papers, as found by Europe PMC text mining. Sharing a sentence is not in itself a finding about the gene and the disease. The quoted sentences say what the papers report.
Ataxia (7 papers, 2017 to 2024). Ataxia refers to impaired coordination of voluntary muscle movement. "Another PMPCA homozygous missense mutation, c.766G>A (p.Val256Met), was identified in two siblings with cerebellar ataxia." (PMID 35163221, 2022). "In the current study, we report a novel homozygous variant in PMPCA gene in a 12-year-old Saudi boy with progressive cerebellar ataxia with frequent falls, slow slurred speech, learning difficulty and fine motor skills difficulties started during his childhood." (PMID 39554679, 2024). "Recently, a novel heterozygous PMPCA variant c.677C>T (p.Arg223Cys) with a deletion of c.853del (p.Asp285Ilefs*16) was reported in a 15-year-old Japanese girl with severe and progressive developmental delay, cerebellar ataxia and extrapyramidal symptoms that seem to represent a new type of SCAR2." (PMID 35163221, 2022). "While further functional investigation and additional patients will help understand the role of PMPCB in ataxic phenotype, we posit that ataxia gene panels would benefit from the inclusion of the gene in a similar fashion to its partner, PMPCA." (PMID 38239855, 2023). "Eleven patients showed very early-onset ataxia and CA with cortical hyperintensities caused by mutations in ITPR1, KIF1A, SPTBN2, PLA2G6, PMPCA, and PRDX3." (PMID 36233161, 2022). "This paradox has already been described in other patients with ataxia and mutations in KIF1A, ITPR1, and PMPCA but also in KCNC3, and CACNA1A genes." (PMID 36233161, 2022). "PMPCA mutants had multisystem impairments, including developmental delay, severe hypotonia, ataxia, lactic acidemia, severe hypertrophic left ventricular cardiomyopathy; Downregulation of MPPα was beneficial to cardiomyocytes during I/R injury." (PMID 34651031, 2021). "The analysis of trio WES data revealed both compound heterozygous variants in PMPCA and a de novo variant in KCND3 in an individual with DD, ataxia, epilepsy, Hirschsprung disease, and abnormal mitochondrial function (Complex I and III deficiency)." (PMID 28327206, 2017). "Recessive pathogenic variants in PMPCA have been described in the context of non-progressive cerebellar ataxia and severe Leigh-like syndrome associated with spastic ataxia." (PMID 35885985, 2022). "At the time of the initial clinical exome analysis, neither PMPCA nor POLR1C were associated with spinocerebellar ataxia and leukodystrophy, respectively." (PMID 28327206, 2017).
developmental delay (3 papers, 2021 to 2024). "Mugdha reported that a patient with mutations in the PMPCA gene, which encodes MPPα, had multisystem impairments, including developmental delay, severe hypotonia, ataxia, lactic acidemia, and severe hypertrophic left ventricular cardiomyopathy and died at 14 months from respiratory failure." (PMID 34651031, 2021).
optic neuropathies (2 papers, 2022 to 2024). "In conclusion, we report the first DOA patients with heterozygous PMPCA variants, confirming the genetic heterogeneity of autosomal inherited optic neuropathies and the important role of mitochondrial import in the maintenance of retinal ganglion cell integrity." (PMID 35885985, 2022).
autosomal recessive cerebellar ataxia (1 paper, 2022). "The literature on the direct role of PMPCA in diabetes is sparse, while a homozygous mutation in PMPCA has been reported to be crucial for autosomal recessive cerebellar ataxia." (PMID 35203577, 2022).
Autosomal Recessive Cerebellar Ataxia type 2 (1 paper, 2022). "In 2015, PMPCA has been identified as the gene responsible for Autosomal Recessive Cerebellar Ataxia type 2 (SCAR2), a severe mitochondrial disease and later for a Leigh-like syndrome with spastic ataxia." (PMID 35885985, 2022). "Recently, PMPCA has been identified as the gene responsible for Autosomal Recessive Cerebellar Ataxia type 2 (SCAR2) and another severe recessive mitochondrial disease." (PMID 35885985, 2022).
diabetes (1 paper, 2022). "Our study provided evidence for the polygenic overlap between diabetic traits and sleep traits, of which the expression of PMPCA may play a crucial role and provide support of the hazardous effect of being an “evening” person on diabetes risk." (PMID 35203577, 2022).
optic atrophy (1 paper, 2022). A disorder characterized by loss of optic nerve fibers. "Again, this is the case for PMPCA, for which we disclosed the involvement of heterozygous variants in a rather late-onset optic atrophy." (PMID 35885985, 2022).
type 2 diabetes (1 paper, 2022). "PMPCA (lead SNP rs10747046), which was downregulated in type 2 diabetes cases, was shared between FG (z score, −4.32; P = 1.53 × 10−5) and chronotype (z score, 4.47; P = 7.79 × 10−6)." (PMID 35203577, 2022). "Two notable pleiotropic genes were ENSA (lead SNP rs2055975) and PMPCA (lead SNP rs10747046), which were differentially expressed in type 2 diabetes cases." (PMID 35203577, 2022). "Two of the pleiotropic genes, ENSA and PMPCA, were validated to be differentially expressed in type 2 diabetes, and PMPCA showed a slight protective effect on type 2 diabetes in MR analysis." (PMID 35203577, 2022). "Intriguingly, both PMPCA and INPP5E showed a significant association with chronotype, which is in opposite directions to type 2 diabetes, indicating that people who are prone to be more an “evening” than a “morning” person have a higher risk for developing type 2 diabetes." (PMID 35203577, 2022). "This may partly explain the pleiotropy of PMPCA in type 2 diabetes and sleep traits." (PMID 35203577, 2022). "Our study showed that both PMPCA and INPP5E showed a significant association with chronotype, which is in opposite directions with type 2 diabetes, which suggested that people who are prone to be more of an “evening” than a “morning” person have a higher risk for developing type 2 diabetes." (PMID 35203577, 2022).
mitochondrial disease (3 papers, 2022 to 2023). "In humans, mutations in either PMPCA or PMPCB cause mitochondrial diseases that are characterized by neurological disorders with early childhood onset and a severe neurodegenerative course." (PMID 35163221, 2022). "However, many tests indicate that mutations in the PMPCA sequence cause incorrect protein processing in mitochondrion and severe mitochondrial diseases." (PMID 37377864, 2023).
PMPCA also shares sentences with these, for which no sentence is quoted: cancer (3 papers); cerebellar ataxia (3); breast carcinoma (2); infection (2); Autosomal Recessive Spinocerebellar Ataxia (1); Brain atrophy (1); cardiomyopathy (1); coronary heart disease (1); COVID-19 (1); Dominant Optic Atrophy (1); epilepsy (1); Failure to thrive (1); Gait ataxia (1); GM2 gangliosidosis (1); Hirschsprung disease (1); intellectual deficiency (1); leukodystrophy (1); liver failure (1); lymphoma (1); multiple sclerosis (1); Nystagmus (1); ophthalmoplegia (1); peripheral neuropathy (1); Salmonella Infections (1); spastic ataxia (1); tumor (1).